RPL21P16 (ribosomal protein L21 pseudogene 16)
Synonyms: Em:AC073587.1; RPL21_38_1104
Gene: Processed pseudogene on chromosome 10 (120,354,701 to 120,355,183, reverse strand). Ensembl gene ENSG00000220842.
Diseases named in the same sentence as RPL21P16 in open-access papers:
RPL21P16 is named in the same sentence as 1 disease in open-access papers, as found by Europe PMC text mining. Sharing a sentence is not in itself a finding about the gene and the disease. The quoted sentences say what the papers report.
infection (1 paper, 2025). The state of being infected such as from the introduction of a foreign agent such as serum, vaccine, antigenic substance or organism. "In contrast, genes such as RNA5S9, RPL7B9, MIR3609, RPS3AP26, and RPL21P16 were commonly found among the top ten differentially expressed genes in both the 16-week post-infection (16wpi) and 24-week post-infection (24wpi) patient groups." (PMID 41141600, 2025).